PTPN9 (protein tyrosine phosphatase non-receptor type 9)
Description:
Protein-tyrosine phosphatase that could participate in the transfer of hydrophobic ligands or in functions of the Golgi apparatus.
Synonyms: MEG2; PTPMEG2
Tractability: Small molecule: a structure with a bound ligand is known; a high-quality ligand is known. PROTAC: ubiquitination databases record sites on it; its protein half-life has been measured; a small molecule that binds it is known.
Target class: Tyrosine protein phosphatase; Enzyme; Phosphatase; Protein Phosphatase
Gene: Protein-coding gene on chromosome 15 (75,463,251 to 75,579,583, reverse strand). Ensembl gene ENSG00000169410.
Subcellular location: Cytoplasm
Subcellular location (Human Protein Atlas): Vesicles
Pathways (Reactome):
Immune System: Interleukin-37 signaling
Gene Ontology:
Molecular function: protein binding; protein tyrosine phosphatase activity; non-membrane spanning protein tyrosine phosphatase activity
Biological process: negative regulation of neuron projection development; peptidyl-tyrosine dephosphorylation; positive regulation of protein localization to plasma membrane; protein dephosphorylation; signal transduction
Cellular component: cytoplasm; neuron projection terminus; nucleoplasm
Genetic constraint (gnomAD): Loss-of-function variants: 21 observed, 57.17 expected, observed/expected ratio (o/e) 0.37, 90% interval 0.26 to 0.53. The upper end of that interval is the gene's LOEUF score, 0.53, which puts it in group 2 of 6, group 1 being the genes least tolerant of losing a copy. Missense variants: 520 observed, 712.31 expected, observed/expected ratio (o/e) 0.73, 90% interval 0.68 to 0.79. Synonymous variants: 261 observed, 269.95 expected, observed/expected ratio (o/e) 0.97, 90% interval 0.87 to 1.07.
Homologues: Orthologues: chimpanzee PTPN9 (100% identical), macaque PTPN9 (99% identical), mouse Ptpn9 (97% identical), rat Ptpn9 (97% identical), pig PTPN9 (97% identical), dog PTPN9 (97% identical), rabbit PTPN9 (95% identical), guinea pig PTPN9 (83% identical), zebrafish ptpn9a (67% identical), tropical clawed frog ptpn9 (60% identical). Paralogues in human: PTPRB (29% identical), PTPRS (28% identical), PTPRF (27% identical), PTPRD (27% identical), PTPRK (27% identical), PTPRZ1 (27% identical), PTPRT (26% identical), PTPRG (26% identical), PTPRM (26% identical), PTPRU (25% identical), PTPRJ (24% identical), PTPRH (24% identical), and 23 more.